ENSG00000222604
Gene: Small nucleolar RNA gene on chromosome 14 (74,711,936 to 74,712,045, forward strand). Ensembl gene ENSG00000222604.
Homologues: Paralogues in human: SNORA7A (63% identical), SNORA7B (63% identical).